CCL5 (C-C motif chemokine ligand 5)
Diseases named in the same sentence as CCL5 in open-access papers (continued):
Sharing a sentence is not in itself a finding about the gene and the disease.
Stroke (45 papers, 2010 to 2025). Sudden impairment of blood flow to a part of the brain due to occlusion or rupture of an artery to the brain. "In fact, the overexpression of CCL5 has been detected in the leukocytes of stroke patients, and this higher expression is associated with stroke severity." (PMID 36077361, 2022). "This clear difference points to CCL5 as a potential diagnostic biomarker to differentiate both stroke manifestations." (PMID 36077361, 2022). "Polymorphisms in the CCL5 gene were associated with stroke risks." (PMID 28072843, 2017). "Interestingly, up-regulated blood CCL5 has also been identified as a risk factor of ischemic stroke that could predict future stroke events." (PMID 37090922, 2023). "Our results indicate that CCL5 downregulation may predispose patients to poor stroke outcome." (PMID 36077361, 2022). "Interestingly, CCL5 was deposited in cerebral vasculature and elevated in systemic circulation and associated with recruitment of leukocytes in mouse models of systemic inflammation and stroke." (PMID 34572077, 2021). "Chemokine CCL5; C-C motif ligand 5, also known as RANTES (regulated on activation, normal T cell expressed and secreted), shows many protective roles after neuronal damage, such as in stroke and AD." (PMID 39285280, 2024). "Injection of a CCL5 inhibitor into tested animals resulted in both a reduction in infarct size and an improvement in neurological outcomes after stroke." (PMID 37759440, 2023). "One interesting pathway from the perspective of neural repair in stroke is the OPC release of CCL5, whose receptor mediates a multilevel neural repair pathway in neurons after stroke." (PMID 37821228, 2023). "Statistically important differences between the CCL5 concentration values in the group of stroke patients compared to the control group were also demonstrated." (PMID 37759440, 2023). "In this study, higher CCL5 concentrations have been observed at 4.5 h, 24 h and on the 7th day after stroke compared to the healthy patients (p < 0.001, 0.001 and 0.005, respectively)." (PMID 37759440, 2023). "CCL5 levels in subgroups of stroke patients with favourable and unfavourable functional status according to the NIHSS." (PMID 37759440, 2023). "The deleterious effect of CCL5 in the acute phase of stroke and the positive correlation between the tested biomarkers of inflammation were also confirmed." (PMID 37759440, 2023). "CCL5 levels in subgroups of stroke patients with favourable and unfavourable functional status according to the mRS." (PMID 37759440, 2023). "CCL5, despite its pleiotropic effects, is of interest to many researchers seeking new therapies focusing on neuronal repair in stroke and traumatic brain injury." (PMID 37759440, 2023). "CCL5 concentrations were compared for different stroke subtypes: lacunar cerebral infarcts (LACI), posterior circulation infarcts (POCI) and partial anterior circulation infarcts (PACI)." (PMID 37759440, 2023). "Our observation that patients with lower levels of CCL5 at admission develop larger stroke volumes, and therefore have a worse prognosis, indicates that in ischemic stroke, CCL5 acts as a neuroprotective factor." (PMID 36077361, 2022). "Chemokine (C-C motif) ligand 5 (CCL5) is a chemokine whose involvement in stroke is attracting interest." (PMID 36077361, 2022). "While these levels did not change in ischemic stroke compared with healthy individuals, there was a large reduction in CCL5 levels in the hemorrhagic stroke patients that lasted for at least 7 days post-stroke." (PMID 36077361, 2022). "Infected mice had elevated Th1-associated cytokines and chemokines after cerebral artery occlusion however, only CCL5 (RANTES) stayed significantly increased after 48 hours post-stroke." (PMID 34078488, 2021). "Stroke caused an increased release of cytokines/chemokines such as CCL and its ligands MCP-1/CCL2, IP-10/CXCL10, and RANTES/CCL5." (PMID 33177990, 2020).
Stroke (continued). "T cell-directed chemokines (including CCL5) are particularly important in stroke prediction including DCI." (PMID 31711504, 2019). "Although CCL5/RANTES concentrations in the brain and plasma were higher in old mice after stroke, leukocyte infiltration was substantially lower, suggesting the possibility of age-related defects in migratory ability." (PMID 29752550, 2018). "Age-related increases in plasma and brain concentrations of CCL5 (RANTES), a pro-inflammatory chemokine involved in leukocyte migration, were found acutely after stroke (SF3); this was only seen in aged mice." (PMID 29752550, 2018). "Previous work has demonstrated a link between circulating CCL5 levels, neutrophil invasion, and the poorer stroke outcome in aged mice; however, this was studied only in the context of chronic peripheral infection." (PMID 29752550, 2018). "Using models of experimental stroke in mice chronic infection increases the severity of stroke and this has been shown to be dependent on the action of CCL5 expression in the brain." (PMID 24942690, 2014). "We observed almost 46-fold and 30-fold increase in CCL5 expression at 24 h and 72 h, respectively, after induction of ET-1 induced stroke model." (PMID 24324296, 2013). "Transcripts for the chemokines CCL3, CCL2 and CCL5 were increased in the ischemic hemisphere of wildtype control mice following stroke, with a peak at 12 h for CCL3 and CCL2 and a peak at 7 d for CCL5." (PMID 23301011, 2013). "As transcriptome sequencing predicated the important function of MAPK pathway in stroke, and previous study has reported that CCL5 can directly initiate M1 polarization and inhibit M2 polarization through the activation of the MAPK pathway via CCR1 and CCR5 receptors." (PMID 41098728, 2025). "Conversely, CCL2 may aid stroke recovery by attracting neural progenitor cells to the brain’s damaged regions, whilst CCL5 can safeguard neurons in per-infarct regions through the production of neurotrophic factors." (PMID 38861234, 2025). "CCL5 level in subgroups of stroke patients depending on clinical parameters." (PMID 37759440, 2023). "Finally, DNT cells contribute to Treg cells recruitment into the ischemic areas through C-C Motif Chemokine Ligand 5 (CCL5) secretion and promote further neural recovery during the chronic stages after stroke." (PMID 36793857, 2023). "Based on this, they concluded that CCL5 may act as a neuroprotective factor in ischemic stroke and that a lower level of CCL5 on admission increases the stroke volume and worsens the patient’s prognosis." (PMID 37759440, 2023). "In addition, we also found such a relationship with IL-6 assessed in less than 4.5 h and on the seventh day, and CCL5 in less than 4.5 h (R = 0.16; 0.22) since the stroke." (PMID 37759440, 2023). "The confirmation of the harmful effect of CCL5 in the acute phase of stroke is supported by the correlation observed between the biomarkers of inflammation, IL-6 and TNF-α, previously determined by our research centre, which is among the first to be released during ischemia in AIS." (PMID 37759440, 2023). "Therefore, we decided to investigate the role of CCL5 through extended clinical follow ups of stroke patients by measuring the CCL5 concentration at different time intervals, <4.5 h, 24 h and the seventh day, and compare them with the control group." (PMID 37759440, 2023). "CCL5 and its ligands can therefore play a dual role in stroke progression." (PMID 37759440, 2023). "It seems that CCL5 may be a good parameter differentiating the types and subtypes of stroke, which is consistent with the literature sources, especially related to haemorrhagic and ischemic stroke as well as ischemic lacunar and cardiogenic stroke." (PMID 37759440, 2023). "Differences in CCL5 levels were found to be dependent on the degree of disability and functional status assessed according to neurological scales (modified Rankin Scale, National Institutes of Health Stroke Scale)." (PMID 37759440, 2023).
Stroke (continued). "In addition, we were unable to find published information on CCL5 levels in different stroke subtypes as well as its impact on patient mortality." (PMID 37759440, 2023). "Elevation of CCL5 in the blood have been documented in multiple central nervous system (CNS) diseases, such as Parkinson's disease, Alzheimer's disease, Multiple sclerosis, stroke, and Traumatic brain injury." (PMID 37090922, 2023). "However, the highest levels of CCL5 were found within the first hours after the appearance of clinical symptoms in stroke patients." (PMID 37759440, 2023). "CCL5/RANTES concentrations significantly increase in old mice after stroke." (PMID 36620775, 2022). "The development of rapid tests for evaluating CCL5 levels may be useful for predicting patient outcomes, developing personalized treatments, and stratifying stroke patients in clinical trials." (PMID 36077361, 2022). "This detrimental effect of CCL5 may be mediated by its modulatory action on the immune system, reactivating other strong pro-inflammatory cytokines, which are important for stroke resolution." (PMID 36077361, 2022). "Furthermore, injecting a CCL5 inhibitor in experimental stroke animals reduced infarct sizes and improved neurological scores after stroke." (PMID 36077361, 2022). "Here, we study whether circulating chemokine (C-C motif) ligand 5 (CCL5) levels may predict clinical outcomes for stroke patients." (PMID 36077361, 2022). "Our study reinforces the view that CCL5 levels do not change significantly in ischemic stroke, although there is a certain trend towards lower levels, especially among females, and the presence of lower levels of CCL5 at admission predicts stroke volume growth." (PMID 36077361, 2022). "Our clinical observations agree with the data obtained from animal experiments, and suggest that during human stroke, CCL5 levels may be neuroprotective and may predict stroke recovery." (PMID 36077361, 2022). "All these results identify CCL5 as a neuroprotective chemokine in stroke." (PMID 36077361, 2022). "Chemokines including macrophage inflammatory protein-1α (MIP-1α or CCL3), monocyte chemotactic protein-1 (MCP-1 or CCL2) and regulated upon activation, normal T-cell expressed, and secreted (RANTES or CCL5) have shown to be released during different models of stroke." (PMID 34572077, 2021). "However, other studies have associated CCL5 and CXCL12 with risk of stroke in human and mouse atherogenesis, promoting cell migration into the brain and induction of cytokines." (PMID 27635404, 2016). "We focused on such factors, i.e. IL-6, CD68, CCL3 and CCL5, which have already been described by us and others occurring in the ischemic peri-infarct area and being relevant for tMCAO-induced brain damage and post-stroke therapy." (PMID 24024100, 2013). "CCL5 may be able to play a neuroprotective role via CCR5 expressed in neurons in the early phase of stroke, while it may worsen neuronal damage by breaking the blood–brain barrier and inducing invasion by inflammatory cells through CCR1 expressed in vascular cells and white blood cells." (PMID 36077361, 2022). "Furthermore, mice receiving young microbiome possessed much higher levels of IL-4 and granulocyte-colony stimulating factor (G-CSF), while the elevation of levels of IL-6, tumor necrosis factor alpha (TNF-α), Eotaxin, and CCL5 were shown in the mice with aged microbiota after stroke." (PMID 33439913, 2021). "Previous findings imply that aging may alter the immunological response to ischemic brain injury, characterized by higher CCL5/RANTES concentrations and increased neutrophil chemotaxis; however, the extent that these age-related changes alter stroke outcomes is unknown." (PMID 29752550, 2018). "FKBP5 and CCL5 modulate p38 MAPK signaling and NET formation, contributing to post-stroke neuroinflammation and neuronal apoptosis." (PMID 41098728, 2025).
Stroke (continued). "Genes related to inflammation such as Ccl5, Cxcl5, Il1a, Tnfsf10, Nfkb1, Tnfrsf1b, Ccr7, Tnfrsf9, Ccl7, Il1b, Il6, and Ccl24 were also downregulated upon MMP-3 KO in male stroke brains." (PMID 39000490, 2024). "CCL5 binds to many receptors in the brain; inhibition of CCR5, one of CCL5’s receptors, benefits recovery after a stroke or TBI in mice." (PMID 39285280, 2024). "The plasma level of CCL5 is highly correlated with BDNF, EGF (epidermal growth factor), and VEGF (vascular endothelial growth factor) after stroke; those trophic factors contribute to neuron growth and proper brain function." (PMID 39285280, 2024). "Evidence is emerging that CCL5 and CCR5 are involved in neurological diseases such as multiple sclerosis, stroke, and Alzheimer's disease." (PMID 36924304, 2023). "At day 22, most of the measured cytokines were slightly (CINC-1, CINC-2α/β, CINC-3, GM-CSF and VEGF) or markedly (CD54, CD62L, CXCL7, CXCL9, CXCL10, CCL3, CCL5, CCL20) induced by stroke compared to Ctl." (PMID 33204331, 2020). "It involves the stroke-mediated decrease of miR-98 and let-7g*, which in turn, triggers expression of pro-inflammatory mediators, such as CCL2, CCL5, CXCL1, and IP-10." (PMID 32766248, 2020). "Numerous chemokines such as CCL5, CXCL4, CXCL7, CX3CL1, (initiation) and CCL2, CCL3, CCL5, CXCL2/3, and CXCL8 (amplification) also contributes to post-stroke inflammation." (PMID 30057552, 2018). "This prompted us to analyze in greater detail the expression levels of well-defined pro-inflammatory mediators during stroke, namely interleukin-6 (IL-6), CD68, CCL3 (MIP1α), and CCL5 (RANTES) by means of rt-PCR." (PMID 24024100, 2013). "The current findings suggest that FKBP5 might modulate CCL5-mediate p38 MAPK signaling and NET formation, thereby contributing to post-stroke neuroinflammation and neuronal apoptosis." (PMID 41098728, 2025). "Impressively, TXL could inhibit the stroke‐enhanced expression of adhesion molecules (P‐selectin and ICAM‐1) and chemokines (CCL‐3, CCL‐4, CCL‐5, and CXCL1)." (PMID 37122157, 2023). "Stroke resulted in upregulated expression of adhesion molecules (P‐selectin, E‐selectin, and ICAM‐1) and chemokines (CC‐chemokine ligand (CCL)‐2, CCL‐3, CCL‐4, CCL‐5, and chemokine C‐X‐C ligand 1 (CXCL‐1))." (PMID 37122157, 2023). "Impressively, TXL could inhibit the expression of stroke‐induced upregulated adhesion molecules (P‐selectin and ICAM‐1) and chemokines (CCL‐3, CCL‐4, CCL‐5, and CXCL1)." (PMID 37122157, 2023). "Despite the lack of change in CCL5 levels in ischemic stroke patients compared with healthy volunteers, we found a significant decrease, at admission, in patients whose stroke volume would grow, thus predicting a poorer outcome." (PMID 36077361, 2022). "Both miRs significantly reduced the stroke-induced increase in CCL2 (p < 0.05) and CCL5 (p < 0.01)." (PMID 32766248, 2020). "Increased levels of CCL5, CCL2, CCL3, and CXCL12 found in the early phase of endothelin-1 induced stroke model were not the cause of neurodegeneration." (PMID 27635404, 2016). "However, the prognostic value of other chemokines, such as CCL2, CCL5, or CXCL8, which have been studied in animal stroke models, remains unclear." (PMID 38861234, 2025). "In addition, differences between various subtypes of stroke were demonstrated, and an increase in CCL5 concentration was proven to be a negative predictor of mortality in patients with AIS." (PMID 37759440, 2023). "Moreover, the lack of unequivocal evidence of the neuroprotective role of CCL5 and its impact on the clinical effectiveness of post-stroke patients provides grounds for determining its levels at different stages of stroke." (PMID 37759440, 2023). "Age-related increases in CCL5 have been previously reported by others and suggest the possibility that neutrophil recruitment may be augmented or altered in old mice following stroke, and this response may not be seen in the young." (PMID 29752550, 2018).
Stroke (continued). "Therefore, studying the mechanisms of CCL5/CCR5 biology that control endothelial cells and the inflammatory response will provide further understanding of the pathophysiology of cardiovascular disease, including stroke, and may assist with developing novel pharmacological strategies." (PMID 36077361, 2022). "Elevated CCL5 content in the blood of people with AIS may be a negative predictor of clinical effectiveness and even an indicator of mortality among stroke patients." (PMID 37759440, 2023). "Although the expression of several studied chemotactic inflammatory mediators (chemokines CCL2, CCL3, CCL5, and CXCL2) was significantly increased in the early stage of this stroke model, there was no clear correlation between this expression and intensity of neurodegeneration (data not shown)." (PMID 24324296, 2013). "They showed upregulation of CCL5 but not CCL2, CCL3, and CCL4 on day 0 in stroke patients." (PMID 24324296, 2013).